BAG3 (BAG cochaperone 3)
Diseases named in the same sentence as BAG3 in open-access papers (continued):
Sharing a sentence is not in itself a finding about the gene and the disease.
tumor (continued). "A recent research by us focused on the role of BAG3 in HCC and demonstrated that BAG3 promoted epithelial–mesenchymal transition, tumor growth, invasiveness, and angiogenesis of HCC." (PMID 24895585, 2014). "The pro-survival role of BAG3 in tumors largely relies on its ability to interact with different partners, some of which are selectively involved in the growth of specific tumor types." (PMID 25149536, 2014). "As a multifaceted protein, BAG3 regulates many biological processes and impacts the progression of tumor in different ways." (PMID 24895585, 2014). "Tissue analysis revealed a correlation of BAG3 with HIF-1α (r = 0.815, P = 0.000), and HIF-1α showed the same change with the level of BAG3 expression in most of the tumor tissue." (PMID 24895585, 2014). "Western blot and immunohistochemical analysis of tumor samples from xenografts treated for 12 days with bag3 siRNA-Ad specifically confirm a reduction of BAG3 protein levels." (PMID 25149536, 2014). "While clearly both effects of BAG3 have to be taken in account when proposing a new therapeutic approach, this goes beyond the scope of this manuscript in which we focused on the role of BAG3 on growth and survival of the primary tumor." (PMID 25149536, 2014). "We then investigated the possibility that in BAG3 positive SCLCs this protein played a pro-survival role as reported for other tumor types." (PMID 25149536, 2014). "We observed that intra-tumoral injection of bag3 siRNA-Ad was able to reduce in vivo tumor growth after 44 days of treatment as compared to the scramble-treated (scr siRNA-Ad) and control groups (p<0.001)." (PMID 25149536, 2014). "The effect of BAG3 down-regulation on tumor growth was also investigated in an in vivo xenograft model by treating mice with an adenovirus expressing a specific bag3 siRNA." (PMID 25149536, 2014). "Evaluation of apoptosis using the terminal deoxynucleotidyl transferase (TdT) FragELTM DNA fragmentation detection kit, an analogue of the TUNEL method, shows that intra-tumoral injection of bag3 siRNA-Ad induced massive apoptotic cell death in tumor cells." (PMID 25149536, 2014). "The 5-year tumor-free survival rate for patients with low expression of BAG3 and for patients with high expression of BAG3 was 62.3% and 25.0% (P = 0.183), respectively." (PMID 24895585, 2014). "The first evidence of a possible involvement of BAG3 in equine sarcoid carcinogenesis was obtained by immunohistochemistry analysis of tumour samples." (PMID 23876161, 2013). "BAG3 is overexpressed in several human tumours, where it sustains cell survival through down-modulation of apoptosis." (PMID 23876161, 2013). "We found that 13 out of 15 tumour samples stained, even though to a different grade, positive for BAG3." (PMID 23876161, 2013). "Evidence of a possible involvement of BAG3 in equine sarcoid carcinogenesis was obtained by immunohistochemistry analysis of tumour samples." (PMID 23876161, 2013). "The central role of BAG3 in cell adhesion pathways and, consequently, in tumour invasion and metastasis, has been previously demonstrated in human epithelial cancer cells." (PMID 23876161, 2013). "Moreover, this subcluster can secrete Bcl2-associated athanogene 3 (BAG3), an important protein that sustains tumor growth and invasion." (PMID 41341850, 2025). "Furthermore, evidence suggests that BAG3 plays a key role in the tumor microenvironment, especially in fibrotic tumor phenotypes frequently seen in HNSCC." (PMID 40507324, 2025). "Consistent with previous findings, genetic depletion of BAG3 led to a significant reduction in tumor sizes, an effect that could partially be mimicked with the two YAP1 inhibitors VK64 and VP." (PMID 38655699, 2024). "Subsequently, KIRC samples of TCGA were divided into BAG3-high and BAG3-low expression groups based on BAG3 expression levels to determine whether different BAG3 expression groups differ in the tumor immune microenvironment of KIRC." (PMID 38297320, 2024).
tumor (continued). "Furthermore, in the stromal fibroblasts, the BAG3 targeting strategy effectively lowered tumor cell survival by modulating CXCL12 levels while nurturing an unfavorable cytokine environment." (PMID 39198407, 2024). "For example, activation of ULK1 may enhance the anti-tumor effect of macrophages, whereas by inhibiting BAG3, the control of AML by immune cells may be enhanced." (PMID 39650664, 2024). "Tumor cells use aerobic glycolysis, a phenomenon known as the Warburg effect, to keep up with their energy demands as they grow and proliferate, and it has been shown that BAG3 shifts malignant cells to aerobic glycolysis." (PMID 36980278, 2023). "The results of GO enrichment analysis showed that BAG3 could inhibit cell apoptosis and promote tumor cell proliferation by binding to HSP70." (PMID 35936896, 2022). "For example, in BC, BAG3 up-regulates the expression levels of Bcl-2 and Bcl-xL by targeting HSP70/Mcl-1 signaling pathway and suppresses the chemoresistance of tumor cells, indicating that BAG3 may be a potential target for treating BC." (PMID 36228497, 2022). "The results of our investigation here reported highlight the potential role of BAG3 in the fibrogenesis of tumor stroma and show how the analysis of bag3 expression could be exploited as a marker of disease progression in patients affected by fibrotic tumors." (PMID 34741483, 2022). "In addition, a study has demonstrated that BAG3 is expressed in HUVECs and regulates tumor neoangiogenesis." (PMID 35893075, 2022). "As noted in the Introduction, we hypothesized that LITAF may link Hsp70 and Bag3 to the macrophage function, including tumor infiltration." (PMID 36077705, 2022). "Indeed, that evidence suggested that extracellular BAG3 is involved in the activation pathway which leads to differentiation of fibroblasts into myofibroblasts, which in turn contribute to tumor fibrosis development." (PMID 34741483, 2022). "Moreover, PRKX binds to enzymes such as Pin-1, Magi-1 and Bag-3, which regulate cell differentiation, proliferation, apoptosis and tumor genesis." (PMID 31964936, 2020). "Additionally, BAG3 expression correlates with tumor stage (TNM grading), differentiation, and metastasis." (PMID 32121220, 2020). "BAG3 silencing also reduced tumor growth in an in vivo xenograft model of SCLC." (PMID 32121220, 2020). "BAG3 appears to maintain tumor growth and regulate metastasis." (PMID 33614490, 2020). "This study shed new light on the tumor-promoting role of BAG3 in PDAC tumors, suggesting BAG3 might represent an interesting therapeutic opportunity to PDAC patients." (PMID 31001483, 2019). "Finally, the most significant upstream factor predicted to be inhibited is the growth factor TGFβ1, confirming the relation between BAG3 silencing and tumor growth repression." (PMID 29487711, 2018). "We hypothesised that BAG3 may regulate tumour cell proliferation by regulating EGFR signalling networks." (PMID 29644001, 2018). "Two of the sections analysed had insufficient tumour present to assess BAG3 expression." (PMID 29644001, 2018). "Due to the high expression of BAG3 observed in a subset of TNBC cell lines and patient samples, we hypothesised that BAG3 might regulate tumour cell proliferation." (PMID 29644001, 2018). "Indeed, the application of an anti-BAG3 monoclonal antibody impaired tumor growth and metastatic spreading in mouse models." (PMID 28680391, 2017). "BAG3 mRNA was significantly higher in most tumor than in peritumor breast tissues." (PMID 28703799, 2017). "Furthermore, in 10 of these patients we observed BAG3 positivity within the tumour tissue increased in metastatic sample in respect to the primary tumour." (PMID 29113311, 2017). "Conversely, activation of the stromal macrophages by BAG3–IFITM‐2 axis promotes tumor growth." (PMID 26747091, 2016). "Importantly blocking this paracrine loopwith an anti-BAG3 antibody results in reduced tumour growth and metastaticspreading." (PMID 26522614, 2015).
tumor (continued). "Furthermore, mice with reduced BAG3 showed suppressed invasion and metastasis of a human tumor xenograft." (PMID 25925243, 2015). "We assumed that BAG3-activated macrophages might release factors that sustainPDAC tumour growth and metastasis formation." (PMID 26522614, 2015). "Finally, we tested if neutralization of PDAC-released BAG3 by an anti- BAG3 mAbalso impairs tumour growth and metastatic spreading in vivo." (PMID 26522614, 2015). "In most studies, BAG3 is demonstrated as a protein favoring tumor progression." (PMID 24895585, 2014). "All of these evidences indicated that the mechanisms of BAG3 in impacting the progression of tumor may involve the HIF-1α signaling pathway." (PMID 24895585, 2014). "Compared with HIF-1α, BAG3 shows a better correlation with tumor size." (PMID 24895585, 2014). "Treatment with bag3 siRNA-Ad significantly reduced tumor growth and improved animal survival." (PMID 25149536, 2014). "We analysed immunohistochemically 15 tumour samples and 5 normal skin samples for BAG3 expression." (PMID 23876161, 2013). "Thirteen out of 15 tumour samples stained positive for BAG3 (85%)." (PMID 23876161, 2013). "We found that most tumour samples stained positive for BAG3, even though to a different grade, while normal dermal fibroblasts from healthy horses displayed very weak staining pattern for BAG3 expression." (PMID 23876161, 2013). "Since BAG3 anti-apoptotic effect in human tumour cell lines has been well established, we aimed at evaluating whether BAG3 might have a pro-survival role also in EqS04b and E. Derm cells." (PMID 23876161, 2013). "Furthermore, BAG3 expression levels frequently correspond with tumor grade and aggressiveness." (PMID 40507324, 2025). "Collectively, BAG3 expression and secretion are characteristic of many neoplasms, and understanding their precise functional roles in diverse tumor types can provide insights into tumor survival mechanisms and inform the development of innovative therapeutic strategies." (PMID 41367874, 2025). "Importantly, BAG3 silencing resulted in reduced tumor neo-angiogenesis." (PMID 36980278, 2023). "In this tumor model BAG3 could be used as a potential target for therapy." (PMID 29487711, 2018). "Bag proteins like Bag1 and Bag3 have been implicated in tumor growth and survival but it is not known whether Bag5 also exhibits this function." (PMID 23448667, 2013). "Next we aimed at verifying whether BAG3 down-regulation, in addition to sensitising cells to basal apoptotic signals, might also increase EqS04b and E. Derm response to drugs, known to promote apoptosis in human tumour-derived cell lines." (PMID 23876161, 2013). "BAG3, a member of the BAG family, regulates tumor cell adhesion, migration, and invasion, promoting recurrence and metastasis." (PMID 40786510, 2025). "Secreted BAG3 can bind to a specific receptor, IFITM2, expressed on macrophages, and induce the release of factors that sustain tumor growth and the metastatic process, most notably BAG3." (PMID 36980278, 2023). "To further explore this possibility, we tested the effects of Bag3 on the expression of the LITAF target CCL2, which plays a major role in tumor development." (PMID 36077705, 2022). "At the hub of our generated network were important tumor-promoting chaperones and co-chaperones such as HSP90, HSP70 and BAG3." (PMID 36114410, 2022). "In this study, we found that Bag3 and LITAF are key contributors to tumor macrophage infiltration which is mediated by the CSF1 pathway." (PMID 36077705, 2022). "The findings using oral squamous cell carcinoma in vitro and in vivo showed that the nanorod improved the sensitivity of tumor cells to PTT and increased apoptosis after through downregulation expression of BAG3." (PMID 36365098, 2022). "On the basis of these theories, we have identified a subtype of TAM (CX3CR1_macro) with abundant production of BAG3, which can combine with IFITM2, leading to tumor metastasis." (PMID 35935940, 2022).
tumor (continued). "Collectively, our results suggested that miR-206 acts as an important tumor suppressor that represses CDDP resistance by affecting the level of CCND2, BAG3, VEGF-A, and other downstream genes of miR-206." (PMID 34746018, 2021). "Silencing of BAG3 evoked a reduction in the migratory and invasive capacity of HCC cells and effectively inhibited tumor growth/metastasis through reduction in CD34 and VEGF expression, events that were associated with a reversion of EMT." (PMID 32121220, 2020). "Here, we describe an anti‐BAG3 humanized mAb able to block BAG3 activity and PDAC tumor growth, providing evidence that BAG3‐ H2L4 humanized antibody is a potential candidate for BAG3‐based targeted therapy in the clinical setting." (PMID 30973679, 2019). "We have previously shown, in several murine models, that blocking BAG3 function results in lowering macrophage infiltrate and cyto/chemokine load in PDAC, thus reducing tumor growth and metastatic spreading." (PMID 30973679, 2019). "We found a correlation between BAG3 and EGFR expression in TNBC cell lines and determined that BAG3 can regulate tumour cell proliferation, migration and invasion in EGFR expressing TNBC cells lines." (PMID 29644001, 2018). "A recent study found that BAG3 can bind to a specific receptor, such as IFITM2, expressed on macrophages, and induce the release of factors that sustain tumor growth and metastasis." (PMID 30081850, 2018). "Similar like BAG3, CXCR4 mRNA was significantly upregulated in breast cancer tumor specimens compared with corresponding non-tumor tissues." (PMID 28703799, 2017). "BAG3 protein, a member of the family of heat shock protein (HSP) 70 co-chaperones that share the BAG domain, is expressed in a wide range of human tumours; in physiological conditions, its expression is conversely narrowed to few cell types (such as myocytes)." (PMID 29113311, 2017). "BAG3 protein, a member of BAG family of co-chaperones, has a pro-survival role in several tumour types." (PMID 29113311, 2017). "BAG3, member the HSP70 co-chaperones family, has been shown to play a relevant role in the survival, growth and invasiveness of different tumor types." (PMID 25149536, 2014). "Since in vitro data showed that down-regulation of BAG3 induces apoptosis in SCLS cells, we investigated the effects of bag3 siRNA-Ad treatment on tumor growth and apoptosis in vivo." (PMID 25149536, 2014). "In this study, we investigate the expression of BAG3 in 66 specimens from different lung tumors and the role of this protein in small cell lung cancer (SCLC) tumor growth." (PMID 25149536, 2014). "Indeed, extracellular BAG3, through interaction with the IFITM2 receptor on macrophages and fibroblasts, fosters a pro-tumorigenic milieu that supports tumor growth, invasion, and immune evasion." (PMID 41367874, 2025). "Moreover, combining extracellular BAG3 blockade with immune checkpoint inhibitors (such as anti-SIRP-α or anti-PD-1 antibodies) yields synergistic enhancement of anti-tumor immune responses beyond immune checkpoint inhibition alone." (PMID 41367874, 2025). "The experiments showed that HSPB8 and BAG3 were highly expressed in ICC and may play a significant role in tumor progression." (PMID 39215616, 2024). "The obtained experimental pieces of evidence show that BAG3 plays an important role in the HS-5-mediated reduction of apoptosis and demonstrates its involvement in the intrinsic survival pathways of B-CLL tumor cells supported by the essential interplay with the stromal microenvironment." (PMID 39198407, 2024). "In line with the limiting effects of BAG3 on tumor growth in vivo, tumors of BAG3‐depleted U251 cells displayed a pronounced decrease in size increases over time (~3 weeks), while ABT‐737 treatment led to the complete elimination of U251‐BAG3 KO tumors." (PMID 38655699, 2024).
tumor (continued). "In this context, the neutralization of extracellular BAG3 is another promising strategy supported by studies carried out in several murine preclinical models treated with an anti-BAG3 mAb, which showed its ability in reducing PDAC tumor growth as monotherapy." (PMID 37835519, 2023). "Administration of anti-BAG3 monoclonal antibodies (mAbs) to pancreatic cancer-bearing animals abated desmoplasia and induced infiltration of CD8+ T lymphocytes and dendritic cells into the tumour nest." (PMID 37554328, 2023). "In our opinion, there is adequate evidence that the BAG3/BAG3R axis is a pro-tumour circuit whose interruption harms the tumour process, but not the homeostasis of healthy cells in the body." (PMID 37554328, 2023). "This hypothetical functional complex consisting of BAG3, HYOU1, GRB2, UBAP2L and DNAJB4 could be very important in PDAC since, in addition to BAG3, interactors also play an important role in tumor pathology." (PMID 35406724, 2022). "What’s more, CX3CR1_macro significantly secreted BAG3, a multifunctional protein, which can combine with a specific receptor IFITM2 to induce the release of factors that sustain the growth and metastasis of tumor." (PMID 35935940, 2022). "Thus, BAG3 is required for GZ17-6.02 -induced autophagy and tumor cell killing, and that BAG3 is required to generate a strong ER stress signal and reduction in HSP90 function." (PMID 35035775, 2022). "Another study analyzing a Chinese cohort of colorectal cancer patients also revealed that BAG3 is higher expressed in tumor compared to non-tumor adjacent tissue." (PMID 32121220, 2020). "The BAG3-mediated activation of macrophages through the PI3K and the p38 MAPK signaling pathways results in secretion of further cell proliferation-stimulating factors, proposing a function of extracellular BAG3 in tumor development." (PMID 28680391, 2017). "In this model, treatment with anti-BAG3, but not with a controlIgG, resulted in highly (>70%) reduced tumour volumes and in complete prevention of metastatic spreading." (PMID 26522614, 2015). "Second, an effective statistical analysis of the patients with BAG3 high-/HIF-1α low- or BAG3 low-/HIF-1α high-expression in tumor is not available." (PMID 24895585, 2014). "Like BAG3, HIF-1α staining was significantly associated with tumor TNM stage (P = 0.012), but not with tumor size (P = 0.22)." (PMID 24895585, 2014). "HDAC6 did not change after Amblyomin-X treatment, but Bag3 increased; this occurred in both tumor cell lines." (PMID 25479096, 2014). "Firstly, a significant correlation between tumor-free survival and the expression level of BAG3 and/or HIF-1α is not observed." (PMID 24895585, 2014). "In addition, high USP32 expression plays a crucial role in tumor growth, metastasis, immune infiltrates, and chemoresistance via the deubiquitination of various substrate proteins, such as Smad2, SHMT2, FDFT1, Rab7, SLC35F2, and BAG3." (PMID 40136417, 2025). "The possible explanation can be that HSP70 works in a network where interaction of HSP70 either with BAG3 or HOP has a positive effect on tumor progression and this is consistent with the idea of HSP70-PC to promote EMT as HSP70 either bound to BAG3 or HOP may still carry a client protein." (PMID 32121660, 2020). "We then analyzed the relationship between BAG3 expression and patient clinicopathological parameters and found that BAG3 expression was closely related to the tumor size and patients’ gender (P < 0.05), though differences in BAG3 expression did not affect patient prognosis." (PMID 30081850, 2018).